IL10 (interleukin 10)
Description:
Major immune regulatory cytokine that acts on many cells of the immune system where it has profound anti-inflammatory functions, limiting excessive tissue disruption caused by inflammation. Mechanistically, IL10 binds to its heterotetrameric receptor comprising IL10RA and IL10RB leading to JAK1 and STAT2-mediated phosphorylation of STAT3. In turn, STAT3 translocates to the nucleus where it drives expression of anti-inflammatory mediators. Targets antigen-presenting cells (APCs) such as macrophages and monocytes and inhibits their release of pro-inflammatory cytokines including granulocyte-macrophage colony-stimulating factor /GM-CSF, granulocyte colony-stimulating factor/G-CSF, IL-1 alpha, IL-1 beta, IL-6, IL-8 and TNF. Also interferes with antigen presentation by reducing the expression of MHC-class II and co-stimulatory molecules, thereby inhibiting their ability to induce T cell activation. In addition, controls the inflammatory response of macrophages by reprogramming essential metabolic pathways including mTOR signaling (By similarity).
Synonyms: IL-10; CSIF; TGIF; IL10A; GVHDS
Tractability: Small molecule: it has a binding pocket of medium quality. Antibody: a drug acting on it is in phase 2 or 3 trials; its Gene Ontology location is reachable by antibodies, with high confidence; UniProt places it where antibodies can reach, with medium confidence; UniProt predicts a signal peptide or a membrane-spanning region.
Target class: Secreted protein
Safety:
Unwanted effects reported when the protein is acted on. In parentheses: how it was acted on, where the effect was seen, and who reports it.
a hypersensitivity reaction to NSAIDs (source: ClinPGx)
Drug Hypersensitivity (source: ClinPGx)
hypersensitivity reaction to NSAIDs (source: ClinPGx)
Gene: Protein-coding gene on chromosome 1 (206,767,602 to 206,774,541, reverse strand). Ensembl gene ENSG00000136634.
Subcellular location: Secreted
Pathways (Reactome):
Disease: CD163 mediating an anti-inflammatory response; FCGR3A-mediated IL10 synthesis; Signaling by ALK fusions and activated point mutants
Immune System: Gene and protein expression by JAK-STAT signaling after Interleukin-12 stimulation; Interleukin-10 signaling; Interleukin-4 and Interleukin-13 signaling
Gene Ontology:
Molecular function: cytokine activity; protein binding; protein dimerization activity; growth factor activity; interleukin-10 receptor binding
Biological process: cellular response to lipopolysaccharide; interleukin-10-mediated signaling pathway; negative regulation of autophagy; negative regulation of B cell proliferation; negative regulation of cytokine activity; negative regulation of cytokine production; negative regulation of cytokine production involved in immune response; negative regulation of endothelial cell apoptotic process; negative regulation of inflammatory response; negative regulation of interleukin-6 production; negative regulation of membrane protein ectodomain proteolysis; negative regulation of MHC class II biosynthetic process; positive regulation of B cell apoptotic process; positive regulation of cytokine production; positive regulation of DNA-templated transcription; positive regulation of immunoglobulin production; positive regulation of miRNA transcription; positive regulation of plasma cell differentiation; positive regulation of receptor signaling pathway via JAK-STAT; positive regulation of transcription by RNA polymerase II; regulation of B cell activation; regulation of complement-dependent cytotoxicity; regulation of gene expression; response to glucocorticoid; response to molecule of bacterial origin; and 45 more
Cellular component: extracellular region; interleukin-10 receptor complex
Genetic constraint (gnomAD): Loss-of-function variants: 7 observed, 18.5 expected, observed/expected ratio (o/e) 0.38, 90% interval 0.21 to 0.71. The upper end of that interval is the gene's LOEUF score, 0.71, which puts it in group 2 of 6, group 1 being the genes least tolerant of losing a copy. Missense variants: 132 observed, 184.56 expected, observed/expected ratio (o/e) 0.72, 90% interval 0.62 to 0.83. Synonymous variants: 77 observed, 75.03 expected, observed/expected ratio (o/e) 1.03, 90% interval 0.85 to 1.24.
Gene-disease validity (ClinGen):
ClinGen rates the evidence that IL10 causes each of these diseases.
IL10-related early-onset inflammatory bowel disease (autosomal recessive): Moderate.
Homologues: Orthologues: chimpanzee IL10 (99% identical), macaque IL10 (96% identical), guinea pig IL10 (83% identical), rabbit IF2A (80% identical), pig IL10 (75% identical), rat Il10 (74% identical), mouse Il10 (73% identical), dog IL10 (61% identical), tropical clawed frog il10 (46% identical), zebrafish il10 (28% identical). Paralogues in human: IL20 (26% identical), IL26 (24% identical), IL24 (21% identical), IL19 (19% identical).
Diseases named in the same sentence as IL10 in open-access papers:
IL10 is named in the same sentence as 1,456 diseases in open-access papers, as found by Europe PMC text mining. Sharing a sentence is not in itself a finding about the gene and the disease. The quoted sentences say what the papers report.
colitis (2,217 papers, 2005 to 2026). Inflammation of the colon. "Other studies have demonstrated that adherent strains of E. coli can increase IL-10 secretion by macrophages, reducing intestinal inflammation and lowering the risk of colitis-associated colorectal cancer." (PMID 41511071, 2026). "Considering the differences in transcriptional cell states and microbiomes, we next sought to test the impact of FLNA editing states on the susceptibility to colitis in an IL-10–deficient background." (PMID 40471139, 2025). "Correspondingly, antibiotic treatment can prevent or mitigate the development of IL-10-deficient colitis in animal models." (PMID 40099014, 2025). "Triptolide has been shown to alleviate colitis in IL-10-deficient mice by inhibiting the IL-6/STAT3 and IL-17 signaling pathways." (PMID 41476955, 2025). "While prior studies showed that IL-22 supports reparative functions in IECs, IL-22 can also mediate inflammation when Treg or IL-10 deficiency causes aberrant macrophage activation and colitis." (PMID 40892518, 2025). "Early research has found that resident enteric baicalin teria are necessary for the development of spontaneous colitis and immune activation in interleukin-10 (IL-10)-deficient mice." (PMID 40099014, 2025). "For example, IL-10 deficiency in C3H/HeJBir and 129/SvEv mice induced severe colitis, whereas BALB/c and 129xC57BL/6J mice developed an intermediate phenotype." (PMID 40671790, 2025). "Specifically, the plant’s ability to fight colitis was linked to higher IL-10, lower IL-6, and lower TNF-α levels." (PMID 40822453, 2025). "For example, the SvEv129 IL-10–/– model of Crohn’s disease develops spontaneous colitis linked with milk-borne MMTV infection." (PMID 39817448, 2025). "The DSS-induced colitis model involves tissue damage and mainly reflects the immunological situation during acute inflammation, while Il10-deficient mice are useful in determining the long-term effects of ongoing inflammation initiated spontaneously." (PMID 40004018, 2025). "It has been reported that Alistipes is negatively linked to IBD and modulates the host lipidome to suppress colitis in an IL-10 deficient mouse model." (PMID 40431355, 2025). "Several lines of evidence support a critical role for IL-10–associated microbiota in the experimental colitis system." (PMID 39895628, 2025). "This pathway facilitates the differentiation of regulatory T cells (Tregs) and IL-10-producing T cells, thereby reducing colitis and colorectal cancer risk." (PMID 40510493, 2025). "IL-10 is an important regulator of intestinal homeostasis, as IL-10 and IL-10R deficient mice spontaneously develop intestinal inflammation and blocking IL-10 signaling induced colitis in Foxp3creCREBfl/fl T cell recipients that were previously resistant." (PMID 40777015, 2025). "T cell transfer into recombinant activating gene (Rag) 1-/- animals or IL-10 deficiency are other murine colitis models commonly used." (PMID 40869366, 2025). "Here, we found that Mcpt-4-deficient colitis mice had significantly higher levels of IL-10 compared to Mcpt-4ΔCre colitis or Mcpt-4fl/fl mice." (PMID 40697820, 2025). "In contrast, Il10-deficient mice develop spontaneous colitis with increased Th1 and Th17 responses and abundant production of proinflammatory cytokines, mimicking human IBD pathogenesis." (PMID 40663408, 2025). "Another study found that HFD induced the expansion of the pathobiont Bilophilia wadsworthia, a sulfur‐producing and bile‐tolerant microbe that provokes a robust Th1 immune response causing colitis in IL‐10 deficient mice." (PMID 40110597, 2025). "The study reported suppression of Klotho expression in three mice models, including the TNBS colitis model, the IL-10 deficient colitis model, and the immunological model of IBD." (PMID 40119098, 2025). "In both mouse and canine DSS-induced colitis models, the probiotic combination significantly reduced weight loss, colonic damage, and serum inflammatory cytokines, while increasing IL-10 levels." (PMID 40395807, 2025).
colitis (continued). "Our findings show that concurrent inactivation of Gsta4 and Il10 (Il10−/−/Gsta4−/−) in mice increases susceptibility to spontaneous colitis under specific pathogen-free conditions." (PMID 39819335, 2025). "As such, CD4+ CD45RBhigh cells, Th1, Th17, and IL-10-deficient CD4+ T cells were transferred into immunodeficient mice to induce colitis." (PMID 40649879, 2025). "Here, our data suggest that the deficiency of Mcpt-4 triggered a stronger Th2 response in colitis as manifested by increased levels of IL-4, IL-5, IL-10, and IL-13, whereas IL-10 is also generally known as an anti-inflammatory cytokine." (PMID 40697820, 2025). "Mice that are deficient in IL-10 exhibit spontaneous colitis, and our experiments revealed that the addition of isobutyrate increased host serum and colon levels of IL-10." (PMID 40342298, 2025). "and the IL-10 deficient mice spontaneously developed symptoms of colitis over time, which were reversed upon IL-10 supplementation." (PMID 40444007, 2025). "Several studies established that mice deficient in IL-10 developed colitis and metformin treatment significantly boosts IL-10." (PMID 40191419, 2025). "Collectively, these results demonstrate that Nfat5 deficiency played a crucial role in the development of IL-10–dependent spontaneous colitis." (PMID 40663408, 2025). "In another in vivo study, microgravity was shown to disrupt intestinal homeostasis, leading to an increase in the pro-inflammatory factor IL-1 and a decrease in anti-inflammatory IL-10 gene expression, which triggered susceptibility to colitis." (PMID 40143237, 2025). "Mannose supplementation was recently linked to improving symptoms of DSS-induced colitis and IL-10 KO IBD models in mice." (PMID 40195978, 2025). "To confirm the interaction of GPR4 and OGR1 in the development of intestinal inflammation we applied the spontaneous colitis model which is driven by IL10 deficiency." (PMID 40004018, 2025). "Mice deficient in IL-10 have increased proinflammatory cytokine production and develop severe colitis." (PMID 39895628, 2025). "Future work employing chronic colitis models, such as DSS-induced colitis or IL-10-deficient mice, will be essential to validate and extend these conclusions." (PMID 41567217, 2025). "Increased IL-10 production by Rorγt-deficient CD4 T cells has been seen in a colitis model in which reduced Blimp-1 expression contributed to this phenotype, but we found similar low levels of Blimp-1 expression by DKO and TKO cells at this timepoint." (PMID 40819821, 2025). "It has been reported that the intestinal symbiotic flora can reduce the susceptibility of mice to experimental colitis through T-cell-derived IL-10." (PMID 39065147, 2024). "The importance of IL-10 is further exhibited by IL-10 deficient mice, which spontaneously develop colitis and exhibit lower RNA and protein levels of tight junction proteins." (PMID 38438107, 2024). "Stard7+/– mice were more susceptible to the development of DSS-induced and Il10–/– spontaneous models of colitis." (PMID 39576011, 2024). "Utilizing STARD7-deficient (Stard7+/–) mice and employing the DSS-induced and Il10–/– spontaneous model of colitis, we found that STARD7 deficiency exacerbated the development of acute and chronic colitis." (PMID 39576011, 2024). "Exposed IS caused colitis in mice, decreasing colon length and IL-10 levels and increasing myeloperoxidase, TNF-α, IL-1β, and IL-6 levels in the colon." (PMID 39519543, 2024). "Previous research has demonstrated associations between A. muciniphila growth, lipocalin-2, and weight loss in DSS-induced colitis, and limited anti-inflammatory activity in IL-10 -/- models." (PMID 39683625, 2024). "The pathogenic or protective roles of DUBA in experimental colitis need to be examined in other types of colitis models, including IL-10-deficient mice and T cell transfer models." (PMID 39403381, 2024).
colitis (continued). "Another Caspase-1-specific inhibitor, namely Ac-YVAD-cmk, suppressed intestinal inflammation and reduced the severity of colitis in Il10-deficient mice." (PMID 39684769, 2024). "The connection between IL-10, asthma onset, and colitis susceptibility in this context merits further investigation." (PMID 39451246, 2024). "In previous studies, IL-10 or IL-2 deficient mice spontaneously develop colitis in a gut bacteria-dependent manner." (PMID 38874761, 2024). "For instance, studies have demonstrated that Aspergillus can induce colitis in IL10-deficient mice fed a high-fat diet, thus highlighting the potential influence of specific microbial strains on disease development." (PMID 39687875, 2024). "Stard7+/–Il10–/– mice exhibited more severe symptoms of colitis and demonstrated exaggerated weight loss before they reached 5–6 weeks of age, indicating that the STARD7 deficiency was associated with early-onset colitis development." (PMID 39576011, 2024). "This was previously documented in both wild-type and colitis-susceptible IL-10−/− mice subjected to ICR." (PMID 38396840, 2024). "More importantly, mice deficient for IL-10 have been shown to display elevated inflammasome activation and IL-1β production resulting in severe colitis or Ag-induced arthritis." (PMID 38372712, 2024). "It has been shown that spontaneous colitis is exhibited in IL-10−/− mice, but colitis does not occur in germ-free IL-10−/− mice, suggesting that the presence of IL-10 inhibits the development of colitis caused by harmful intestinal bacteria." (PMID 39591319, 2024). "IL-10 is known for its anti-inflammatory effects, and a deficiency in IL-10 can lead to spontaneous colitis in mice." (PMID 38710918, 2024). "In this model, CX3CR1+ macrophages serve as a cellular source of IL-23, akin to the scenario observed in the IL-10-deficient colitis model." (PMID 39379604, 2024). "In these IL-10-deficient colitis models, suppression of IL-12 and IFN-γ production and induction of tolerogenic DCs by GIN infection were proposed to limit disease severity." (PMID 38277692, 2024). "Irrespective of the rBanLec treatment, induction of experimental colitis in both strains was associated with a simultaneous rise in local production of both TNFα and IL-10." (PMID 38892639, 2024). "Monoassociation with L. plantarum in gnotobiotic IL-10-/- mice causes considerable immune system activation but minimal colitis." (PMID 38398870, 2024). "IL-10-deficient mice show more severe infection symptoms, such as diarrhea and colitis, suggesting that IL-10 has a regulatory role in controlling the inflammatory response during giardiasis." (PMID 39201314, 2024). "Inflammatory responses in models such as the DSS-induced colitis model and Il10−/− mice are exacerbated upon inhibition or deficiency of IL-17A, suggesting a pivotal role for IL-17A in maintaining the integrity of the gut barrier." (PMID 39379604, 2024). "Conversely, upregulation of IL-10 expression has been shown to reduce the risk of colitis-associated cancer." (PMID 38710918, 2024). "B. vulgatus increased epithelial barrier permeability in vitro and induced colitis in a mono-colonized IL-10 deficient mouse model; both features were reversed by administration of a broad-spectrum protease inhibitor cocktail." (PMID 39135000, 2024). "In models of spontaneous colitis in IL-10-KO mice, STING deficiency is associated with reduced intestinal inflammation." (PMID 39050748, 2024). "IL-10 deficiency on the BL6 background causes less severe colitis symptoms than on the SV129 background, which is likely a result of less severe alterations in clock gene expression." (PMID 38918576, 2024). "It was demonstrated that a deletion in miR-106a-5p will enhance Treg induction and IL-10 production, and attenuate colitis in T cell-restricted deficiency." (PMID 39259390, 2024).